EWSR1 (EWS RNA binding protein 1)
Diseases named in the same sentence as EWSR1 in open-access papers (continued):
Sharing a sentence is not in itself a finding about the gene and the disease.
tumor (continued). "The alternative splicing of EWSR1 may play a role in the pathogenesis of associated tumors and transcript variants might be differentially expressed in various tumor types, influencing tumor behavior and progression." (PMID 39769457, 2024). "One report also identified a case of an INI-1 deficient tumor with and EWSR1-PLAGL1 rearrangement." (PMID 38639853, 2024). "Similarly, John R. Goldblum and colleagues reported a high frequency (9/11) of ALK positivity in AFH, which is an EWSR1 (or rarely FUS) rearrangement-associated neoplasm characterized by accompanying lymphoplasmacytic infiltrate." (PMID 37120571, 2023). "The EWSR1-FLI1low cells are supposedly mesenchymal-like and have a transcriptional signature and phenotype associated with cell migration, invasion, and seeding, properties that are ultimately needed for a tumor to metastasize." (PMID 33801953, 2021). "This is based on their capability to endure expression of EWSR1-ETS gene chimera without additional mutations, and the finding that transient EWSR1-ETS expression leads to a tumor similar to EWS at the level of expressed cellular markers and micro-array expression data." (PMID 26193259, 2015). "Indeed, copy numbers of cell‐free EWSR1‐ETS fusion sequences correlate with patients’ risk factors such as tumor volume, pelvic tumor, and metastatic status, and most EwS patients show a fast reduction of cfDNA levels during treatment, while recurrence of increasing cfDNA levels indicates relapse." (PMID 33047515, 2020). "Here, we report that tissue-specific expression of EWSR1::FLI1 in zebrafish induces tumor formation that recapitulates the histologic and molecular hallmarks of human ES, including small round blue cell morphology and characteristic biomarker expression." (PMID 41977317, 2026). "Markers of proliferation and expression of EWSR1 fusion target genes were consistent with the tumours from which PDES were derived (R2 = 0.74, p < 0.0001) and the paediatric mesenchymal lineage (SBS5 and SBS1, ID1 and ID2)." (PMID 41681984, 2026). "Fluorescence in situ hybridization (FISH) analysis using a break-apart probe targeting EWSR1 revealed red–green split signals in 93% of tumor cell nuclei, indicating the presence of an EWSR1 gene rearrangement." (PMID 40429661, 2025). "In contrast, the EWSR1::AFF2 fusion tumor showed high-grade adenocarcinoma morphology with focal neuroendocrine marker expression, lacking p63 and CK5/6." (PMID 40494991, 2025). "Gastrointestinal clear cell sarcoma is a rare tumor with neuroectodermal differentiation that affects the gastrointestinal tract and involves gene fusion translocations of EWSR1." (PMID 40443852, 2025). "The tumor with an EWSR1::POU5F1 fusion (case 7) contained nested clear to eosinophilic tumor cells with EMA and S100 expression but was negative for other myoepithelial markers." (PMID 39636306, 2025). "This molecular distinctiveness – coupled with the tumor’s ventricular localization and glioneuronal morphology – provides strong support for classifying EWSR1::PATZ1-fused tumors as a unique clinicopathological entity." (PMID 40575153, 2025). "The myoepithelial‐like morphology of these tumors, their stromal characteristics, and their bland morphology are reminiscent of features seen in some NFATC2::EWSR1/FUS fusion neoplasms of bone and soft tissue." (PMID 40944358, 2025). "In summary, an EWSR1::CREB fusion epithelial-like tumor originating from the kidney is an “exclusively” diagnosable condition." (PMID 41341384, 2025). "Four cases (67%, 4/6) showing EWSR1 amplification of 5′ end of the EWSR1 locus were from tumours in the femur." (PMID 40666501, 2025). "FISH allows for the precise detection of EWSR1 gene recombination, aiding in tumor characterization." (PMID 39958930, 2025). "With the widespread use of RNA sequencing technology, the EWSR1/FUS::CREB fusion mesenchymal tumor family has expanded rapidly to include potentially aggressive tumors rather than any well-established WHO entity." (PMID 41341384, 2025).
tumor (continued). "FISH technology serves a vital role in pathological research, particularly in detecting recombination in the EWSR1 gene, a significant genetic alteration commonly observed across various tumor types." (PMID 39958930, 2025). "DNA sequencing of the tumor tissue identified a fusion involving exons 1–16 of EWSR1 and exon 12 of PSMC5." (PMID 39877461, 2025). "In case 3 microscopy, 50% of the tumor cells exhibited separation of red and green signals, indicating fragmentation of the EWSR1 gene." (PMID 39963393, 2025). "Emerging evidence has highlighted the pivotal role of the EWSR1/Ezrin signaling axis in tumor progression and metastasis." (PMID 40762284, 2025). "Recognizing the secondary EWSR1 gene abnormalities in SMARCB1-deficient tumors can avoid misinterpretation of EWSR1 gene FISH assay and misclassification of the tumor." (PMID 40366517, 2025). "Mechanistically, several of these CNAs appear to be positively selected during tumor evolution because they buffer replication or mitotic stress induced by the EWSR1::FLI1 fusion." (PMID 41301081, 2025). "Tumour cells are thought to reside in a dynamic and metastable state fluctuating between ‘high’ or ‘low’ EWSR1::FLI1 expression." (PMID 40442778, 2025). "We assessed for potential differences in patient and tumor characteristics and outcomes based on the fusion partner (e.g., EWSR1 or FUS)." (PMID 40361368, 2025). "FET::ETS fusions, including EWSR1::ERG have also been reported in the newly emerging superficial neurocristic FET::ETS fusion tumor." (PMID 40640075, 2025). "Zebrafish and cell-based systems provide direct evidence that loss of EWSR1 promotes LOH and aneuploidy via AURKB -dependent mitotic defects, while human tumor profiles confirm selection for conditions that allow CIN." (PMID 41301081, 2025). "Next, western blot analysis was conducted to evaluate EWSR1 protein expression across various tumor cell lines." (PMID 41472850, 2025). "Fifth, distinguishing FET::CREB fusion neoplasms reported herein from other well-defined EWSR1 fusion entities in the morphological spectrum of SEF-like neoplasms requires more than MUC4 immunohistochemistry and EWSR1 FISH testing." (PMID 39031200, 2024). "Recently, a group of intra-abdominal FET(EWSR1/FUS)::CREB(CREM/ATF1) fused unclassified neoplasms has been reported followed by recent recognition of an analogous extra-abdominal category of unclassified neoplasms carrying EWSR1::ATF1 fusions." (PMID 39249507, 2024). "Almost all of these entities can be distinguished from EWSR1::SMAD3-rearranged fibroblastic tumor based on typical morphological and immunohistochemical features." (PMID 39264472, 2024). "The tumor's morphology and immunoprofile, along with molecular findings, led to a diagnosis of round cell sarcoma with EWSR1-CREM fusion." (PMID 38674190, 2024). "Transfection experiments with other, structurally related EWSR1 chimeras, like EWSR1::FLI1, support this concept, although the detailed underlying mechanism, including the list of chimera-dysregulated tumor-driver genes, is still to be elucidated." (PMID 39769457, 2024). "The tumor was further evaluated using targeted RNA-seq in order to identify the gene fusion partner, revealing a fusion transcript EWSR1::BEND2 between EWSR1 exon 11 and BEND2 exon 5 (Table A1)." (PMID 38339014, 2024). "A total of 100 tumor cell nuclei were counted and 78% of nuclei showed split signals, indicating EWSR1 gene rearrangement." (PMID 39493091, 2024). "Ubiquitous EWSR1::ATF1 induction by either TAT-Cre or tamoxifen (for CreER) injection resulted in tumor formation and additional developmental deformities." (PMID 38916046, 2024). "The only exception is cellular fibrous histiocytoma, which can closely resemble EWSR1::SMAD3-rearranged tumor morphologically and regularly show diffuse expression of ERG." (PMID 39264472, 2024).
tumor (continued). "We herein describe 4 unclassified extra-abdominal soft tissue (n = 3) and bone (n = 1) neoplasms displaying epithelioid and round cell morphology and carrying an EWSR1::ATF1 fusion." (PMID 39031200, 2024). "Ultimately, three patients died of disease, all of whom underwent a subtotal resection for an EWSR1::ATF1 fusion-positive tumor." (PMID 38291529, 2024). "Median tumor size was 3.6 cm (0.3–11.1 cm), and 24/26 (94%) tissues analyzed at our institute were EWSR1::ATF1-translocation-positive." (PMID 39535601, 2024). "The frequent presence of EWSR1 locus abnormalities in a wide range of histopathologically distinct human neoplasms mandate EWSR1 chimeras as valid therapeutic targets for tumor-agnostic therapeutic measures." (PMID 39769457, 2024). "The results of next-generation sequencing of tumor tissue showed that the EWSR1 and FLI1 genes were fused to form a new gene with transcriptional function." (PMID 38769118, 2024). "We verified that EWSR1 was also associated with HCC patient survival prognosis and promoted tumor proliferation and invasion." (PMID 38460179, 2024). "Case 1 was tested initially by a FISH probe targeting the EWSR1 rearrangement, which revealed red-green split signals in 96% of the tumor cell nuclei, indicating EWSR1 gene rearrangement." (PMID 39031200, 2024). "Recent RNA-sequencing data compared primary and recurrent DSRCT samples as well as cell lines suggesting the EWSR1::WT1 fusion protein as a principal driver with enrichment in genes regulated by the fusion protein in the recurrent versus primary tumor." (PMID 39411551, 2024). "Evaluation of the clinical outcome of these patients revealed STR, younger age (< 14 years old), infratentorial location, and possible EWSR1::ATF1 fusion as poor prognostic factors for this recently defined tumor type." (PMID 38291529, 2024). "Among the 74 IMT cases reported to date, three patients eventually died of disease, all of whom underwent a STR for an EWSR1::ATF1 fused tumor." (PMID 38291529, 2024). "Here, we review our current knowledge of human malignancies carrying the specific subset of EWSR1 rearrangements that leads to the expression of the EWSR1::ATF1 tumor-driver chimeric protein." (PMID 39769457, 2024). "Accordingly, EWSR1/FUS::CREB fusion neoplasms are not well known in the female genital tract pathology literature and are, hence, possibly under-recognized." (PMID 37097347, 2023). "The EWSR1/FUS-CREB fusion family of neoplasms have been ever expanding to encompass a variety of histologically, immunophenotypically, biologically, and topographically distinct entities." (PMID 37097347, 2023). "Although a tumor-specific target, EWSR1::FLI1-targeted therapy has yet to be developed, largely due to insufficient understanding of EWSR1::FLI1 upstream and downstream signaling, and the challenges in targeting transcription factors with small molecules." (PMID 36672331, 2023). "Unexpectedly, we detected increased copy numbers of EWSR1 locus in many neoplasm cells of ES-RMS, which is a more intriguing phenomenon, as until now, no increased copy numbers of EWSR1 gene were identified in any case in the English literature." (PMID 36998041, 2023). "Screening of 24 cases of pulmonary HCCC with EWSR1 fusion revealed that five cases demonstrated lymph node metastases and only two had documented tumor recurrences." (PMID 37553667, 2023). "Additional tumor types with BEND2 fusions include single-case reports of unclassified basal cell-like salivary gland adenocarcinoma with a EWSR1::BEND2 fusion and one spindle cell soft tissue sarcoma with MN1::BEND2 fusion." (PMID 36690805, 2023). "The molecular hallmark of this tumor, present in over 90% of cases, is the fusion of NR4A3 with EWSR1 at 22q12.2 or TAF15 at 17q12." (PMID 37484580, 2023). "Intra-tumor heterogeneity is a well-established tumor characteristic that has been applied to the different expression levels of EWSR1::FLI1 that exist in EwS cells." (PMID 36915100, 2023).
tumor (continued). "Instead, further molecular genetic testing showed that the tumor harbored a rare EWSR1::CREM fusion combined with a previously unreported IRF2::NTRK3 fusion." (PMID 37274229, 2023). "We evaluated the panel using tumor DNA samples from five patients (four with EWSR1 fusions and one with a FOXO1 fusion, as previously identified by OncoKids®34)." (PMID 36805676, 2023). "The main population in the tumor would be constituted by tumor cells with high levels of the chimeric protein (EWSR1::FLI1high phenotype) and characterized by elevated proliferation and an undifferentiated cellular status." (PMID 37511533, 2023). "The detection of EWSR1 fusion transcript expression by RT-qPCR is a common method for MRD detection in EWS tumours." (PMID 34471258, 2022). "In the last decade, new tumor entities have been described, including EWSR1/FUS::NFATC2-rearranged neoplasms of different biologic behavior." (PMID 36555836, 2022). "Our study supports and expands previously reported molecular findings of EWSR1/FUS::NFATC2-rearranged neoplasms." (PMID 36555836, 2022). "Our results indicate that the presence of EWSR1 gene amplification or gene copy number changes is found only in biologically aggressive neoplasms." (PMID 36555836, 2022). "We found that consistent with human data the EWSR1-FLI1-expressing cells in tumor were also positive for nkx2.2a (EWSR1-FLI)." (PMID 35285802, 2022). "Meanwhile, with EWSR1 break-apart probe, the fluorescence in situ hybridization analysis revealed EWSR1 translocation in about 85% of tumor cells." (PMID 36343072, 2022). "Herein, we presented a case of EWSR1::SMAD3-rearranged fibroblastic tumor that recurred twice in a 20-year-old man." (PMID 36591513, 2022). "This means that the percentage of positive cells is below the cutoff of 15% (10–12% for EWSR1) or that 0% positive tumor cells were detected (for FUS, CIC, and BCOR)." (PMID 36232302, 2022). "EWSR1 is strongly expressed in HCC, it is associated with histological grade and pathological T stage, and it is considered a novel tumor prognostic marker." (PMID 36211823, 2022). "We presented a recurrent intracranial EWSR1-PLAGL1 rearranged tumor and reviewed the relevant literature." (PMID 35912228, 2022). "EWSR1 rearrangements with different partner genes are related to different phenotypes of neoplasms, namely small-cell, spindle-cell, clear-cell phenotype or neoplasms with distinctive myxoid stroma." (PMID 34374640, 2022). "In our study, we analyzed a biological spectrum of bone and soft tissue EWSR1/FUS::NFATC2-rearranged neoplasms." (PMID 36555836, 2022). "Immunohistochemistry with CD99 and EMA plays a limited role, as both benign and malignant EWSR1/FUS::NFATC2-rearranged neoplasms can stain positive." (PMID 36555836, 2022). "EWSR1::SMAD3-rearranged fibroblastic tumor is a recently described entity that mostly occurs in acral locations." (PMID 36591513, 2022). "Although the literature reports that RT–PCR has a higher failure rate than FISH (described in EWSR1-rearranged neoplasm), in this study the failure rates of the two methods are comparable." (PMID 36614077, 2022). "EWSR1 is the most common gene that can generate various fusion genes and is evident in a variety of neoplasms." (PMID 33715971, 2022). "A large proportion of CCOC have also been shown to have EWSR1 rearrangements, similar to that found in clear cell salivary gland carcinoma, suggesting that these tumours despite their differing locations, are somewhat related." (PMID 33736630, 2021). "As oncogenic transformation mediated by EWSR1-fusion proteins leads to such diverse tumor types, there must be a selection on the multipotent stem cell level." (PMID 34203801, 2021). "The application of chemotherapy in ES patients reduced the tumor volume, as depicted in CT and MRI scans, and diminished the circulating EWSR1 fusion sequence levels measured via droplet digital PCR." (PMID 34768955, 2021).
tumor (continued). "Noteworthy, the expression of EWSR1 was found to be closely related to aggressive factors and mortality, further illustrating that EWSR1 expression is positively correlated with poor tumor differentiation and advanced clinical stage." (PMID 34612781, 2021). "We examined the tumor for EWSR1/ATF1 transcripts using RT-PCR and direct sequencing on the paraffin-embedded tissue." (PMID 33478436, 2021). "The original report comparing CIC-DUX4 and EWSR1-NFATc2 positive tumors identified key molecular markers differentiating the two diseases; presenting PAX7 as a highly specific marker for EWSR1-NFATc2 positive tumor diagnosis." (PMID 34021224, 2021). "To determine if AR regulation of the EWSR1 gene is through direct binding, we analyzed published AR ChIP-seq datasets from patient tumor samples and matched adjacent normal tissue." (PMID 34409300, 2021). "We, therefore, believe it to be likely that these MN1:PATZ1 and EWSR1:PATZ1 fusions are pathognomonic for this novel tumor type." (PMID 34417833, 2021). "Sequence analysis confirmed that tumors 1 and 2 had EWSR1-FLI1, tumor 3 had EWSR1-FEV, and tumors 5 and 6 had EWSR1-ERG." (PMID 34749732, 2021). "Based on the publicly available data, as well as in primary tissue samples, we demonstrate that EWSR1 is overexpressed in HCC, and is associated with high histological tumor grade and short overall patient survival." (PMID 34612781, 2021). "As oncogenic transformation mediated by EWSR1-fusion proteins leads to such diverse tumor types, there must be a selection on a multipotent stem cell level." (PMID 34203801, 2021). "In our cohort, the degree of tumor differentiation was lower in patients with high expression of EWSR1 as compared with those in the EWSR1 low-expression group." (PMID 34612781, 2021). "FISH showed a clear separation of red and green signals within a single tumor cell, demonstrating the presence of a EWSR1 gene rearrangement." (PMID 32039736, 2020). "Circ-CUX1 can directly interact with EWSR1 and facilitate EWSR1-MAZ interaction, resulting in transactivation of MAZ and transcriptional alteration of CUX1 and other genes associated with tumor progression." (PMID 32547943, 2020). "Split red and green signals within a single tumor cell demonstrated the presence of EWSR1 rearrangement." (PMID 32039736, 2020). "Fluorescence in situ hybridization (FISH) using an EWSR1 probe revealed a split signal in the tumor cells: seemingly an EWSR1 gene fusion." (PMID 33025168, 2020). "EWSR1 is also known to be translocated in 13 other tumour types with at least 17 other fusion partners, common partners being, WT1, ATF1, CREB1, YY1, NFATC2, and others." (PMID 33488267, 2020). "Genetically, the tumor is characterized by translocations involving the EWSR1 gene in over 90% of cases." (PMID 31236300, 2019). "Dual-colored fluorescence in situ hybridization (FISH) analysis using EWSR1 break-apart probes (Abbott Molecular, Abbott Park, IL) on FFPE tissue detected EWSR1 split signals in 94% of the tumor cells." (PMID 31103034, 2019). "A FISH was performed on formalin-fixed paraffin-embedded tumour tissues and found a translocation of EWSR1, which was confirmed by the next-generation sequencing (NextSeq 550 System, illumina) and correspond to the fusion transcript EWSR1/ATF1." (PMID 31350293, 2019). "FISH analysis of EWSR1 breakapart probe on paraffin-embedded tumour tissue showed evidence of a 22q12 rearrangement in 164 out of 200 (82%) of interphase nuclei scored." (PMID 28946910, 2017). "Fluorescent in situ hybridization tests proved the breakpoint rearrangement of the EWSR1 gene in chr 22.Ultrastructural analysis revealed neurosecretory and glycogen granules in the tumor cell cytoplasm." (PMID 28472972, 2017). "Kaplan-Meier analysis of the Kocak (n=476) and Versteeg (n=88) NB tumor gene expression datasets revealed that high EWSR1 transcript levels strongly correlate with poor survival." (PMID 29212266, 2017).